CRP (C-reactive protein)
Diseases named in the same sentence as CRP in open-access papers (continued):
Sharing a sentence is not in itself a finding about the gene and the disease.
brain injury (17 papers, 2013 to 2025). Acute and chronic (see also brain INJURIES, CHRONIC) injuries to the brain, including the cerebral hemispheres, CEREBELLUM, and brain STEM. "Additionally, CRP measured early after trauma is particularly useful in assessing diffuse brain injuries, as higher levels are found in patients with low GCS scores and poor clinical outcomes." (PMID 39335744, 2024). "Therefore, we conducted this double-blind, placebo-controlled, randomized trial to assess the possible effects of early melatonin administration on the levels of biomarkers, including MDA, S100B, and C-reactive protein (CRP) in patients with brain injuries." (PMID 35517892, 2022). "A cortisoltotal/CRP > 3 ratio upon admission may predict the development of HAP in patients with severe traumatic brain injury." (PMID 31805967, 2019). "In patients with severe traumatic brain injury, ulinastatin treatment could effectively improve cerebral oxygen metabolism and reduce CRP level." (PMID 27340674, 2016). "Plasma concentrations of TNF-α, IL-6 and CRP in subjects without injury or following control trauma and traumatic brain injury were determined." (PMID 23894384, 2013). "The innovation of this study lies in the integration of inflammatory biomarkers (IL-6, CRP, NSE), providing mechanistic insights into neuroprotection and systemic inflammatory modulation, strengthening the study’s translational relevance for traumatic brain injury management." (PMID 40443507, 2025). "Furthermore, in our cohort, CRP, NLR, and WBC showed a close correlation with admission periostin levels, indicating a possible link between the early immune response and post-ischemic brain injury." (PMID 36010292, 2022). "According to our data selenium and CRP may not play a role in progression of coma state in patients with severe traumatic brain injury." (PMID 29875918, 2018).
bronchopneumonia (17 papers, 2006 to 2025). Acute inflammation of the walls of the terminal bronchioles that spreads into the peribronchial alveoli and alveolar ducts. "In our case, the initial misdiagnosis of bronchopneumonia, which was based on clinical presentation, CT imaging, and elevated CRP levels, highlights the diagnostic challenges inherent to BMS." (PMID 41404591, 2025). "Early work showed median C-reactive protein (CRP) values >30 mg/L in children who later developed bronchopneumonia." (PMID 40872832, 2025). "The CRP level in group of interstitial pneumonia was significantly higher than that in groups of bronchopneumonia and hilar shadow thickening (P = .003 and P = .001 respectively)." (PMID 33545964, 2021). "The results of this study revealed that neonates with bronchial pneumonia showed greatly increased CRP and ESR levels, indicating that they suffered from systemic inflammatory response." (PMID 34745505, 2021). "The median CRP level increased to 4.85 μg/mL (range: 1.19–16.56 μg/mL) in bronchopneumonia." (PMID 38250933, 2024). "In addition, the diagnostic accuracy on neonates with bronchial pneumonia using only CRP or ESR levels was only about 75%, while that of CRP + ESR + CT examination could be as high as 98.6%." (PMID 34745505, 2021). "The levels of CRP and ESR in peripheral blood of neonates with bronchial pneumonia were 27.3 ± 3.5 mg/L and 19.1 ± 3.7 mm/h, respectively." (PMID 34745505, 2021). "Compared with the healthy neonates, the levels of CRP and ESR in the peripheral blood of neonates with bronchial pneumonia were much lower (P < 0.05)." (PMID 34745505, 2021). "After comparison, it was found that the CRP and ESR levels in peripheral blood of neonates with bronchial pneumonia were remarkably lower in contrast to the healthy neonates (P < 0.05)." (PMID 34745505, 2021). "Compared with the bronchopneumonia group, the segmental/lobar group recorded lower WBC count (p = 0.04), absolute lymphocyte count (1,900 ± 1,300/μL vs. 2,700 ± 1,700/μL, respectively; p < 0.001), and platelet count (p = 0.02), but higher CRP (2.1 ± 2.3 vs. 5.1 ± 5.3 mg/dL, respectively; p < 0.001)." (PMID 20604923, 2010).
Cervical lymphadenopathy (17 papers, 2015 to 2026). Enlarged lymph nodes in the neck. "Ten days after completing therapy, she experienced a new episode of fever, cough, and cervical lymphadenopathy with elevated C-reactive protein levels." (PMID 40149127, 2025). "She had repeated fevers and showed high levels of C-reactive protein (CRP) with cervical lymphadenopathies." (PMID 38510957, 2024). "In our patient, an extensive microbiological evaluation was performed, given the initial presentation with a fever, rash, cervical lymphadenopathy, elevated CRP, and cytopenias, all of which could be attributed to an infectious etiology." (PMID 40508215, 2025). "Here, significant differences were noted between the two groups for PLT, WBC, ESR, CRP, TBIL, GGT, fever days, IVIG days, sex, conjunctival injection, and cervical lymphadenopathy." (PMID 40144928, 2025). "Statistically significant variables including age, cervical lymphadenopathy, NLR, PLR, CRP, TBil, Na+, and ALB were enrolled in multivariate logistic regression analysis." (PMID 33712036, 2021). "SII was identified as an independent risk factor for valve regurgitation after adjusted by age, the presence of cervical lymphadenopathy, WBC, CRP, ALT, TBil (p < 0.001)." (PMID 34504878, 2021). "Persistent UTE in the absence of other clinical signs could be further investigated with cervical USS to investigate for cervical lymphadenopathy and blood tests to include FBC, CRP and LDH." (PMID 40178376, 2025). "In isolated UTE, reassuring ultrasound scan (USS) investigating for cervical lymphadenopathy and the absence of abnormal investigations including FBC, CRP and LDH, may advocate for observational management of children rather than diagnostic tonsillectomy." (PMID 40178376, 2025). "However, there were no significantly different between cervical lymphadenopathy and ALT, CRP, ESR, Ferritin, respectively (P-value: 0.16, 0.88, 0.2,0.47)." (PMID 36585531, 2022).
clear cell renal cell carcinoma (17 papers, 2006 to 2025). "Similarly, in metastatic clear-cell renal cell carcinoma, higher baseline CRP levels were associated with significantly worse OS and PFS in patients treated with nivolumab." (PMID 41009716, 2025). "In this study, we investigated the influence of CRP on the tumor microenvironment in clear cell renal cell carcinoma (ccRCC)." (PMID 39564003, 2024). "Several studies have revealed that CRP is detected in clear cell renal cell carcinoma (ccRCC) tissues and that there is a positive correlation between CRP expression in tumor tissues and poor prognosis in patients." (PMID 39564003, 2024). "A recent study has shown that higher CRP levels indicate an immunosuppressive tumor microenvironment in patients with clear cell renal cell carcinoma." (PMID 33635904, 2021). "The IL-6/JAK/STAT signaling pathway has been reported to enhance CRP expression in glioblastoma, clear cell renal cell carcinoma and gastroesophageal cancers." (PMID 33013829, 2020). "CRP regulates cell apoptosis and cell-cycle in clear cell renal cell cancer." (PMID 33013829, 2020). "Moreover, C-reactive protein may offer a useful preoperative therapeutic target in patients undergoing potentially curative surgery for renal clear cell cancer." (PMID 16523196, 2006). "However, a positive correlation between CRP level and FOXP3+ cell tumor infiltration has been observed in clear cell renal cell carcinoma (RCC)." (PMID 32316975, 2020).
cystic fibrosis (17 papers, 2014 to 2026). Autosomal recessive disorder caused by pathogenic variants in the CFTR gene (cystic fibrosis transmembrane conductance regulator), which encodes a chloride and bicarbonate channel expressed in epithelial cells, and follow the diagnosis criteria. "High levels of C-reactive protein are associated with lower forced expiratory volume in the first second in individuals with cystic fibrosis." (PMID 29267535, 2018). "Associations between the C-reactive protein/albumin ratio and lung function, nutritional status, positive culture for Pseudomonas aeruginosa and hospitalization among patients with cystic fibrosis have been little investigated." (PMID 29267535, 2018). "The objective of the present study was to investigate whether C-reactive protein (CRP) level was associated with the severity of pulmonary exacerbation requiring admission to hospital in patients with cystic fibrosis." (PMID 25248567, 2014). "In the present study, we investigated the potential association between CRP level and the severity of pulmonary exacerbations requiring hospital admission in patients with cystic fibrosis and ascertained whether CRP level was associated with specific clinical characteristics." (PMID 25248567, 2014). "No previous studies in which the C-reactive protein/albumin ratio was evaluated among children/adolescents with cystic fibrosis were found, although determination of C-reactive protein and albumin levels forms part of routine hospital evaluations." (PMID 29267535, 2018). "Multicenter studies need to be conducted in order to evaluate the applicability of the C-reactive protein/albumin ratio among children/adolescents with cystic fibrosis in clinical practice." (PMID 29267535, 2018). "The continuous inflammatory response and persistent inflammation in individuals with cystic fibrosis lead to an imbalance in cytokine levels, thus stimulating hepatic production of acute-phase proteins, such as C-reactive protein." (PMID 29267535, 2018). "A significant increase of in-hospital FEV1, home spirometry FEV1, and body-mass index and a significant decrease of the modified Fuchs symptom score, C-reactive protein, and 8 out of the 12 domain scores of the revised cystic fibrosis questionnaire were demonstrated after 28 days." (PMID 37107096, 2023). "In this study we tested the hypothesis that in patients with cystic fibrosis (pwCF) respiratory rate (RR) is associated with antibiotic treatment, exacerbation status, forced expiratory volume in one second (FEV1) and C-reactive protein (CRP)." (PMID 35148739, 2022). "Also, elevated levels of S100A8/A9 in plasma of cystic fibrosis patients compared to healthy controls were found and the high levels correlated with high sputum production and C-reactive protein." (PMID 29180999, 2017). "Additionally, CRP titers have not been associated with pulmonary exacerbation severity, but have with specific clinical characteristics in cystic fibrosis patients." (PMID 37873776, 2023). "C-reactive protein (CRP) is a systemic marker of inflammation that correlates with disease status in cystic fibrosis." (PMID 28178305, 2017). "In stable adult cystic fibrosis patients, we assessed the role of baseline high sensitivity C-reactive protein (hs-CRP) on CF clinical variables and frequency of intravenous (IV) treated pulmonary exacerbations (PExs) 1-year post-baseline." (PMID 28066689, 2016). "In this case report, a suspected patient with ambiguous respiratory symptoms underwent a comprehensive investigation revealing elevated CRP levels, TLC, and characteristic pulmonary manifestations on chest X-ray, suggesting cystic fibrosis." (PMID 39351067, 2024). "There is a lack of studies evaluating the C-reactive protein/albumin ratio among children/adolescents with cystic fibrosis." (PMID 29267535, 2018). "The median C-reactive protein/albumin ratio was also higher in the cystic fibrosis group, but the difference was not significant (P = 0.077)." (PMID 29267535, 2018).
cystic fibrosis (continued). "A recent publication on inflammation and microbiota in pulmonary exacerbations in patients with cystic fibrosis found that those who had a high concentration of P. aeruginosa colonies had lower FEV1 values and higher CRP values, in contrast with the remaining bacteria studied." (PMID 25248567, 2014). "The authors suggest that chemerin may correlate with the severity of cystic fibrosis, but this was only based on the levels of CRP without examining for correlations of chemerin with lung function testing or a history of infections." (PMID 40564073, 2025).
glomerulonephritis (17 papers, 2010 to 2025). A renal disorder characterized by damage in the glomeruli. "They found associations between a low expressing CRP allele and more severe glomerulonephritis and an interactive effect between this CRP allele and the low IgG-binding FcγRIIIA allele (F/F)." (PMID 24167754, 2013). "This work clearly established a predominant effect of CRP on ongoing renal pathology and showed a similar protective effect of CRP in accelerated nephrotoxic nephritis (NTN), an immune complex-mediated glomerulonephritis that is not autoimmune in nature." (PMID 24167754, 2013).
Hypofibrinogenemia (17 papers, 2006 to 2025). Decreased concentration of fibrinogen in the blood. "In both diseases, the albumin and LDH levels were significantly higher and the CRP levels were significantly lower in patients with hypofibrinogenemia than in those without hypofibrinogenemia." (PMID 33632246, 2021).
hypovitaminosis D (17 papers, 2012 to 2025). "A meta-analysis suggested that increased high-sensitivity CRP might be a risk factor for hypovitaminosis D, consistent with the outcomes reported in this review." (PMID 40867540, 2025). "Increased CRP have been associated with decreased 25-OH vitamin D levels, which may suggest that supplementing vitamin D may improve inflammatory status and cardio-vascular risk in SZ subjects with hypovitaminosis D." (PMID 30190688, 2018). "Hypovitaminosis D was associated with high inflammatory activity (SLEDAI, ESR, CRP, IL-6), severity of organ damage (DI), cumulative dose of GCs, BTMs (OC, CTX) and BMD." (PMID 37558268, 2023). "In our study, CRP was significantly higher in patients with hypovitaminosis D, and an inverse correlation between 25OHD levels and CRP was observed." (PMID 35140702, 2021). "According to our results, hypovitaminosis D (independently of BMI status) was associated only with increased adiponectin levels and not with other biomarkers of inflammation and oxidative stress (WBC counts, CRP, MCP-1, MPO, I-TAC, SOD-1)." (PMID 39408928, 2024). "Hypovitaminosis D is quite common in patients with SLE and is associated with high inflammatory activity (SLE Disease Activity Index, ESR, CRP, IL-6), severity of organ damage (Damage Index), cumulative dose of glucocorticoids, BTM changes (decrease in OC, increase in CTX) and BMD decline." (PMID 37558268, 2023). "We found higher levels of s-VAP 1 in hypovitaminosis D, but hs-CRP levels were unchanged." (PMID 26000307, 2015). "Some cross-sectional studies indicate that hypovitaminosis D is associated with higher serum levels of inflammatory biomarkers, such as IL-6, TNF-α, and C-reactive protein (CRP), in healthy and in obese subjects, while others could not confirm these findings." (PMID 22347618, 2012). "Furthermore, some subjects showed changes in novel and non-traditional CVRF, namely elevation of Lp(a), hs-CRP, homocysteine, fibrinogen and B-type natriuretic peptide, hypomagnesemia, and hypovitaminosis D, which can help to reclassify individuals or individually identify greater risk." (PMID 35371626, 2022).
intracranial hemorrhage (17 papers, 2011 to 2025). Bleeding within the SKULL, including hemorrhages in the brain and the three membranes of MENINGES. "Additionally, routine inflammatory markers such as C-reactive protein (CRP) are often pathologically increased postoperatively due to trauma or, in the case of an intracranial hemorrhage." (PMID 40257674, 2025). "It must be noted that admission CRP levels were significantly increased in patients with no change/poor outcomes and in patients with therapy-associated intracranial hemorrhage as compared to healthy controls." (PMID 33669007, 2021).
metastatic carcinoma (17 papers, 2007 to 2025). A carcinoma which has spread from the original site of growth to another anatomic site. "Generally, in gastrointestinal cancer, increased CRP is associated with progressive disease, advanced stages of metastatic cancer, and poor survival." (PMID 37873776, 2023). "Very high CRP levels are associated with advanced, poorly responding metastatic cancers.CRP exists in two main forms: pentameric CRP (pCRP), the anti-inflammatory circulating form, and monomeric CRP (mCRP), which emerges during inflammation and is pro-inflammatory." (PMID 41367907, 2025). "Elevated CRP levels have been linked especially to metastatic rather than non-metastatic cancer highlighting a particular importance of CRP as a systemic marker in advanced metastatic cancer." (PMID 37382699, 2023). "It should be highlighted that several other studies have reported significantly elevated CRP in secondary metastatic cancers, and also it has been proposed as a marker for further metastases and worse outcomes." (PMID 37873776, 2023). "Combined AE and RT in non-metastatic cancer patients during chemotherapy, a decline in the CRP was observed in the intervention group." (PMID 35935260, 2022). "Analyzed in a multivariate logistic regression model, older age, metastatic cancer, a depressed level of consciousness, higher CRP and higher creatinine levels on admission were all independently associated with treatment outside a CD." (PMID 33396830, 2020). "Considering that patients with metastatic cancer often present with elevated baseline C-reactive protein levels, advanced age, and chemotherapy-induced immunosuppression, signs of infection may not always be apparent." (PMID 40094888, 2025). "Finally, pretreatment high levels of CRP predict both the lack of IL-2 activity on tumour objective response and its efficacy on overall survival in metastatic cancer patients." (PMID 17953739, 2007).